DIP2B (DIP2 acetate--CoA ligase B (putative))
Description:
Negatively regulates axonal outgrowth and is essential for normal synaptic transmission. Not required for regulation of axon polarity. Promotes acetylation of alpha-tubulin.
Synonyms: KIAA1463; FLJ34278
Tractability: PROTAC: ubiquitination databases record sites on it; its protein half-life has been measured.
Gene: Protein-coding gene on chromosome 12 (50,504,962 to 50,748,657, forward strand). Ensembl gene ENSG00000066084.
Subcellular location: Cell projection, dendrite; Cell projection, axon; Perikaryon
Subcellular location (Human Protein Atlas): Endoplasmic reticulum
Gene Ontology:
Molecular function: alpha-tubulin binding
Biological process: negative regulation of axon extension; positive regulation of peptidyl-lysine acetylation
Cellular component: cytoplasm; extracellular exosome; membrane; nucleus; axon; dendrite; perikaryon
Genetic constraint (gnomAD): Loss-of-function variants: 75 observed, 202.82 expected, observed/expected ratio (o/e) 0.37, 90% interval 0.31 to 0.45. The upper end of that interval is the gene's LOEUF score, 0.45, which puts it in group 1 of 6, group 1 being the genes least tolerant of losing a copy. Missense variants: 1,558 observed, 2,064.9 expected, observed/expected ratio (o/e) 0.75, 90% interval 0.72 to 0.79. Synonymous variants: 701 observed, 766.46 expected, observed/expected ratio (o/e) 0.91, 90% interval 0.86 to 0.97.
Homologues: Orthologues: macaque DIP2B (99% identical), dog DIP2B (99% identical), pig DIP2B (99% identical), chimpanzee DIP2B (98% identical), mouse Dip2b (98% identical), rat Dip2b (98% identical), rabbit DIP2B (97% identical), guinea pig DIP2B (92% identical), tropical clawed frog dip2b (88% identical), zebrafish dip2ba (81% identical), zebrafish dip2bb (79% identical), Drosophila melanogaster DIP2 (57% identical), and 1 more. Paralogues in human: DIP2C (72% identical), DIP2A (71% identical).
Diseases named in the same sentence as DIP2B in open-access papers:
DIP2B is named in the same sentence as 30 diseases in open-access papers, as found by Europe PMC text mining. Sharing a sentence is not in itself a finding about the gene and the disease. The quoted sentences say what the papers report.
Intellectual disability (4 papers, 2017 to 2024). "Furthermore this observation is interesting as decreased expression levels of both DIP2C and DIP2B are associated with mental retardation." (PMID 28716088, 2017).
cervical squamous cell carcinoma (2 papers, 2021 to 2023). A squamous cell carcinoma arising from the cervical epithelium. "In addition, bioinformatics analysis has implicated Dip2b as a target gene in the metastasis of cervical squamous cell carcinoma." (PMID 34208944, 2021). "Interestingly, DIP2B has been identified as a potential susceptibility gene associated with colorectal cancer, and the epigenetic modifications of DIP2B mediated by miRNAs may be implicated in the metastasis of cervical squamous cell carcinomas." (PMID 37004015, 2023). "Several bioinformatics studies have also discovered associations between DIP2B and numerous diseases, including schizophrenia, coronary artery disease (CAD), cervical squamous cell carcinoma, and colorectal cancer." (PMID 34208944, 2021).
colorectal cancer (2 papers, 2012 to 2023). A primary or metastatic malignant neoplasm that affects the colon or rectum. "We next sought to dissect the mechanisms by which natural variation in 3′-end usage impacted gene expression, using as case studies IRF5 and DIP2B, which lie in genomic regions associated with susceptibility to lupus and colorectal cancer, respectively, as well as NAB1 and EIF2A." (PMID 22916029, 2012).
coronary artery disease (2 papers, 2020 to 2021). "Integrative functional analysis of super-enhancer SNPs has shown Dip2b to be a novel functional locus for coronary artery disease." (PMID 34208944, 2021). "Defect in DIP2B was also discovered in several bioinformatics studies on disease models including schizophrenia, coronary artery disease (CAD), cervical squamous cell carcinoma, and colorectal cancer." (PMID 33153107, 2020).
developmental delay (2 papers, 2018 to 2023). "We exemplify the power of 5-base HiFi-GS in unsolved rare disease cases by identifying a hyper-mCpG event that caused LREA and led to a previously undiagnosed pathogenic allele in DIP2B causing global developmental delay." (PMID 37248219, 2023). "On average 30–40 rare hypermethylation tiles overlap rare disease genes per patient, providing indications for variation prioritization including a previously undiagnosed pathogenic allele in DIP2B causing global developmental delay." (PMID 37248219, 2023).
breast carcinoma (1 paper, 2023). "Knockdown of the DIP2B gene induced a reduction in proliferation and migration and an increase in apoptosis in breast cancer cell lines." (PMID 37004015, 2023). "Immunohistochemistry was performed to detect DIP2B protein expression and subcellular localization in breast cancer tissues." (PMID 37004015, 2023). "We investigated the effect of DIP2B silencing on the migration of the four breast cancer cell lines using a scratch assay." (PMID 37004015, 2023). "DIP2B knockdown by siRNA was performed in breast cancer cell lines to investigate the effect on proliferation, apoptosis and migration." (PMID 37004015, 2023). "To analyse the role of DIP2B in the proliferation of breast cancer cells, we performed CCK-8 assays." (PMID 37004015, 2023). "Genes coexpressed with DIP2B were also enriched in cell cycle-related pathways, including MITOTIC_SPINDLE, G2M_CHECKPOINT and E2F_TARGETS, which means that breast cancer cells with high expression of DIP2B showed stronger proliferative activity." (PMID 37004015, 2023). "However, we also observed consistently in all four classic breast cancer subtype cell lines that cell proliferation and migration capacity were significantly decreased after DIP2B knockdown in vitro, while the percentage of cell apoptosis was increased." (PMID 37004015, 2023). "In conclusion, DIP2B might be considered an oncogene and used as a prognostic biomarker in breast cancer." (PMID 37004015, 2023). "The results showed that DIP2B protein was expressed in the cytoplasm of breast cancer cells." (PMID 37004015, 2023). "We noted that both high mRNA expression and high protein expression of DIP2B were associated with poor prognosis in the Her-2 + breast cancer subtype, but the same was not true in other subtypes." (PMID 37004015, 2023). "A total of 39.2% (47/120) of breast cancer samples showed high expression of DIP2B." (PMID 37004015, 2023). "The biological function of DIP2B was studied in breast cancer cell lines." (PMID 37004015, 2023). "DIP2B expression predicts a cold tumour microenvironment, and DIP2B might serve as a potential target gene to improve the response of immunotherapy in breast cancer." (PMID 37004015, 2023). "Thus, what we have confirmed to date is that DIP2B is an oncogene in breast cancer, especially in the Her-2 + breast cancer subtype." (PMID 37004015, 2023).
chromophobe renal cell carcinoma (1 paper, 2023). Chromophobe renal cell carcinoma is a rare subtype of renal cell carcinoma, originating from the intercalating cells of the collecting ducts and macroscopically manifesting as a well-circumscribed, highly lobulated, solid tumor that is usually diagnosed at an early stage. "DIP2B was highly expressed in 26 of 33 cancer types and was significantly associated with poor overall survival (OS) in breast invasive carcinoma (BRCA), mesothelioma and chromophobe renal cell carcinoma (each P < 0.05)." (PMID 37004015, 2023).
colon cancer (1 paper, 2025). "Of them, 10 aging-related CpG sites were mapped to 6 genes (i.e., TNF, BICC1, TBX3, SUCNR1, NCF2, DIP2B), and the altered methylation of cg03037030 located in TNF was associated with the risk of CRC, colon cancer, and rectal cancer, with consistent effect direction." (PMID 41197401, 2025).
Cyanosis (1 paper, 2020). Bluish discoloration of the skin and mucosa due to poor circulation or inadequate oxygenation of arterial or capillary blood. "Direct observation of litters from Dip2btm1a/+ intercross revealed cyanosis in Dip2b homozygotes, suggesting a lack of proper oxygenation due to circulatory or respiratory dysfunction." (PMID 33153107, 2020).
intrauterine growth restriction (1 paper, 2020). "Target disruption of Dip2b leads to intrauterine growth restriction, defective lung formation and perinatal mortality." (PMID 33153107, 2020). "Knockout of Dip2B results in an intrauterine growth restriction and neonatal death possibly due to respiratory insufficiency." (PMID 33153107, 2020). "In this study, we have discovered that mouse homozygous inactivation of Dip2B exerts intrauterine growth restriction and death of newborns within a few hours due to abnormal lung pathology and neonatal respiratory distress (NRD)." (PMID 33153107, 2020).
lymph node metastasis (1 paper, 2023). "High expression of DIP2B protein was significantly associated with high histological grade and lymph node metastasis (each P < 0.05)." (PMID 37004015, 2023). "DIP2B expression was associated with lymph node metastasis and poor histological grade in BRCA according to immunohistochemistry (each P < 0.05)." (PMID 37004015, 2023).
metastasis (1 paper, 2023). The spread or migration of cancer cells from one part of the body (where they first appeared) to another. "Immunohistochemical results of patient samples showed that the high DIP2B expression group of had an increased probability of lymph node metastasis, poor tumour differentiation and poor prognosis." (PMID 37004015, 2023).
respiratory failure (1 paper, 2020). The significant impairment of gas exchange within the lungs resulting in hypoxia, hypercarbia, or both, to the extent that organ tissue perfusion is severely compromised. "Given the decreased expression of Sfpta1, Sfptb and Sftpd, it is possible that Dip2b deletion might alter the activity of secreted surfactants, which is likely associated with respiratory failure at birth." (PMID 33153107, 2020).
schizophrenia (1 paper, 2021). A major psychotic disorder characterized by abnormalities in the perception or expression of reality. "A previous report suggested that Dip2b may play a role in mental retardation and in schizophrenia." (PMID 34208944, 2021).
cancer (2 papers, 2014 to 2023). A tumor composed of atypical neoplastic, often pleomorphic cells that invade other tissues. "The implications of DIP2B expression in different cancers should be discussed separately and fully verified." (PMID 37004015, 2023). "Gene coexpression analysis was further conducted to explore the relationship between DIP2B expression and tumour immune-related genes across cancers." (PMID 37004015, 2023). "Further analysis showed that the expression of DIP2B was positively correlated with infiltration of some immune cells, including neutrophils in 13 cancer types and macrophages M1 cells in 6 cancer types." (PMID 37004015, 2023). "Herein, we comprehensively and systematically investigated the role of DIP2B mRNA expression in 33 human cancers." (PMID 37004015, 2023). "The expression levels of DIP2B in 33 cancer types were analysed based on data sets from The Cancer Genome Atlas (TCGA) and the Genotype-Tissue Expression (GTEx) database." (PMID 37004015, 2023). "GSVA revealed that genes positively correlated with DIP2B were enriched in cancer-related pathways (PI3K-AKT) and proliferation-related pathways (MITOTIC_SPINDLE, G2M_CHECKPOINT and E2F_TARGETS) in BRCA." (PMID 37004015, 2023). "Our study comprehensively analysed the relationship between DIP2B expression and prognosis in 33 cancer types by bioinformatics." (PMID 37004015, 2023). "DIP2B showed a positive correlation with tumour purity in most cancer types, which means that DIP2B is mainly expressed in cancer cells." (PMID 37004015, 2023). "The expression of DIP2B in 33 human cancers was analysed using TCGA and GTEx data sets." (PMID 37004015, 2023). "There have been many reports on DIP2B in various diseases, but neither the diagnostic value nor the prognostic value of DIP2B across cancer types has been deeply explored." (PMID 37004015, 2023). "We found that DIP2B was highly expressed in 26 cancer types compared with normal tissues." (PMID 37004015, 2023). "DIP2B expression was associated with poor OS according to both Cox analysis and KM survival analysis in BRCA, KICH and MESO; therefore, our further pancancer analysis of the DIP2B gene was focused on these three cancer types." (PMID 37004015, 2023). "The relationship between DIP2B expression and the OS of cancer patients was estimated." (PMID 37004015, 2023). "DIP2B was correlated with different immune-related genes in different cancer types." (PMID 37004015, 2023). "However, the diagnostic value and prognostic value of DIP2B across cancers have not been deeply explored." (PMID 37004015, 2023). "However, the effect of DIP2B expression on immune infiltration in primary cancer tissues is still unknown." (PMID 37004015, 2023). "We found that genes positively correlated with DIP2B were enriched in the PI3K-AKT pathway; when this pathway is overactive, as is the case in many cancers, apoptosis is suppressed and proliferation and migration are enhanced." (PMID 37004015, 2023). "Therefore, we considered that DIP2B might play different roles in different cancers." (PMID 37004015, 2023). "DIP2B showed a positive correlation with tumour purity and a negative correlation with immune score in most cancers, including BRCA." (PMID 37004015, 2023). "However, DIP2B expression was negatively correlated with key immune killer cells, including CD8 T cells in 20 cancers, activated NK cells in 17 cancers, and plasma cells in 9 cancers." (PMID 37004015, 2023). "In BRCA, the GSVA results revealed that genes correlating positively with DIP2B were enriched in cancer-related pathways (PI3K-AKT) and cell-cycle-related pathways (MITOTIC_SPINDLE, G2M_CHECKPOINT and E2F_TARGETS), while genes correlating negatively with DIP2B were enriched in DNA_REPAIR." (PMID 37004015, 2023).
tumour (1 paper, 2023). "DIP2B is associated with a “cold” tumour immune microenvironment in BRCA and might serve as a future target for immunotherapy." (PMID 37004015, 2023). "We considered that DIP2B expression predicted a “hot” tumour immune microenvironment in KICH." (PMID 37004015, 2023). "The correlation between DIP2B expression and the tumour immune microenvironment was discussed." (PMID 37004015, 2023). "Therefore, specifically decreasing the expression of DIP2B in tumour cells is the first challenge." (PMID 37004015, 2023). "However, there are few reports about the expression and role of DIP2B in tumours." (PMID 37004015, 2023). "DIP2B showed a positive correlation or tendency with tumour purity and a negative correlation or tendency with immune score in five subtypes of BRCA." (PMID 37004015, 2023).
DIP2B also shares sentences with these, for which no sentence is quoted: autism (1 paper); brain disorder (1); diabetes (1); epilepsy (1); fragile X syndrome (1); leukemia (1); lupus (1); mesothelioma (1); Neonatal respiratory distress (1); neurodevelopmental disorder (1); oculopharyngodistal myopathy 1 (1); pulmonary hypertension (1); rectal cancer (1); Respiratory insufficiency (1).